PTH (parathyroid hormone)
Diseases named in the same sentence as PTH in open-access papers (continued):
Sharing a sentence is not in itself a finding about the gene and the disease.
familial isolated hyperparathyroidism (1 paper, 2024). A rare, autosomal dominant hereditary syndrome characterized by hypercalcemia, abnormally high levels of parathyroid hormone, and isolated hyperfunctioning parathyroid tumors. "Variants of GCM2, a parathyroid-specific embryonic transcription factor, increase the transactivation of the PTH promoter in vitro and are associated with familial isolated hyperparathyroidism (FIHP; OMIM#614373 HRPT4)." (PMID 39409111, 2024).
giant cell tumors of the (1 paper, 2023). "And the present report emphasized the importance of distinguishing BTs from other giant cell tumors of the bone and the relevance of measuring serum calcium and parathormone (PTH) before the diagnosis of osteolytic bone lesions." (PMID 36820584, 2023). "In summary, the present report emphasized that in patients presenting with a vertebral lesion, BT should be considered in the differential diagnosis, especially when giant cell tumors are considered, serum calcium and PTH exam may be needed to exclude BTs." (PMID 36820584, 2023). "BTs might be misdiagnosed as other giant cell tumors, thus when giant cell tumors are considered, serum calcium and PTH examination may be needed to exclude BTs." (PMID 36820584, 2023).
Hematuria (1 paper, 2019). The presence of blood in the urine. "Another major limitation is that, we could not obtain information on the cause of hematuria and other laboratory results (e.g., calcium, phosphorous, parathyroid hormone and 1,25 OH Vitamin D level) which may have an interaction in the relationship results." (PMID 31126256, 2019).
hemolysis (1 paper, 2021). Disruption of the integrity of the erythrocyte membrane causing release of hemoglobin. "To conclude, we confirm a high prevalence of pHPT among our SCD population, with a biological pattern including high serum calcium, inadequate PTH levels and subnormal calcitriol concentrations, and a strikingly low FeCa2+, which is associated with chronic hemolysis biomarkers." (PMID 34768698, 2021).
Hirsutism (1 paper, 2025). Abnormally increased hair growth referring to a male pattern of body hair (androgenic hair). "Over a 12-week period, the treatment group showed significant decreases in total testosterone, parathyroid hormone, free androgen index, and hirsutism scores." (PMID 40337376, 2025).
HIV-1 infection (1 paper, 2019). The type species of lentivirus and the etiologic agent of acquired immunodeficiency syndrome (AIDS). "Alterations in VitD metabolism during HIV-1 infection is associated with an increase in proinflammatory cytokines which block the effect of the parathyroid hormone (PTH) and the hydroxylation of calcidiol in the kidney, preventing the synthesis of active VitD." (PMID 31611877, 2019).
hookworm infections (1 paper, 2022). "We also did not collect information that may have influenced vitamin D or iron status such as dietary intake, sunlight exposure or hookworm infections and did not measure 1,25(OH)2D, FGF23, vitamin D binding protein, parathyroid hormone, or calcium concentrations." (PMID 35405984, 2022).
Hyperparathyroidism-jaw tumor syndrome (1 paper, 2025). "Hyperparathyroidism-jaw tumor syndrome (HPT-JT) is a rare autosomal dominant endocrine neoplastic disorder characterized by increased values of PTH due to neoplasms of parathyroid glands, in 10% to 50% of cases ossifying fibromas of the jaws and in 15% neoplasms of the kidneys and/or the uterus." (PMID 40115416, 2025).
ischemia (1 paper, 2014). A hypoperfusion of the BLOOD through an organ or tissue caused by a PATHOLOGIC CONSTRICTION or obstruction of its BLOOD VESSELS, or an absence of BLOOD CIRCULATION. "Since CD34+/Flk1+ ESCs/EPCs increased in the circulation and pro-angiogenic factors were elevated in the brain by PTH, we tested the hypothesis that post-ischemia angiogenesis could be enhanced after chronic PTH treatment." (PMID 24503654, 2014).
Kidney Cyst (1 paper, 2021). Abnormal fluid filled sac within the kidney, either acquired or congenital. "One possible mechanism by which cinacalcet suppressed kidney enlargement in the present cohort is by lowering the level of PTH in serum, which leads to reduced tubular activation of PTH1R and cAMP production in kidney cyst cells." (PMID 33976330, 2021).
knee osteoarthritis (1 paper, 2020). "In daily clinical practice, VD, PTH, and bone density are very rarely evaluated in patients with hip or knee osteoarthritis and lumbar degenerative spinal stenosis scheduled for surgical intervention." (PMID 32923255, 2020).
leukemia (1 paper, 2023). A malignant (clonal) hematologic disorder, involving hematopoietic stem cells and characterized by the presence of primitive or atypical myeloid or lymphoid cells in the bone marrow and the blood. "In addition to that of PTH, the role of bisphosphonates in leukemia remains unclear." (PMID 36918531, 2023).
lumbar intervertebral disc degeneration (1 paper, 2016). "Oestrogen and PTH treatment can retard the progression of lumbar intervertebral disc degeneration in OVX rats, improve the proportion of notochord cells and enhance Wnt/β-catenin pathway activity in the NP." (PMID 27279629, 2016).
lymphadenopathies (1 paper, 2018). "The final patient was followed-up for 15 months and presented with multiple lymphadenopathies in the neck, with a serum PTH level of 88 pmol/L and calcium level of 3.17 mmol/L." (PMID 30290620, 2018). "The mean serum PTH was 165.14 ± 90.26 pmol/L (range: 46–263 pmol/L), which declined rapidly after surgery in 3 patients (mean: 1.38 ± 1.1 pmol/L, range: 0.3–1.5 pmol/L) but remained high in one patient (147.5 pmol/L) who presented with multiple lymphadenopathies in the neck." (PMID 30290620, 2018).
malignant fibrous histiocytoma (1 paper, 2022). "We previously reported the possible existence of a new lncRNA located downstream of the human parathyroid hormone (PTH) gene in ectopic PTH-producing malignant fibrous histiocytoma (MFH)." (PMID 35618021, 2022).
malignant primary brain tumors (1 paper, 2024). "Higher PTH associated with inferior EFS in primary malignant brain tumors [HR, 1.80 (1.19–2.72)], embryonal malignancies [HR, 2.20 (1.1–4.43)], and lymphatic malignancies [HR 1.98 (1.05–3.72)]." (PMID 39141058, 2024). "PTH levels ≥47 pg/mL (PTH+ group) at any time within the first 5 years following the cancer diagnosis were associated with significantly inferior EFS in the groups: embryonal malignancies, lymphatic malignancies, and malignant primary brain tumors." (PMID 39141058, 2024).
mediastinal tumor (1 paper, 2023). "However, the serum intact PTH level after parathyroidectomy did not decrease to normal; therefore, we performed MIBI scintigraphy again and recognized accumulation in the upper mediastinal region, which revealed that the mediastinal tumor was an ectopic parathyroid gland." (PMID 37341946, 2023).
Miscarriage (1 paper, 2022). A pregnancy that ends at a stage in which the fetus is incapable of surviving on its own, defined as the spontaneous loss of a fetus before the 22th week of pregnancy. "Regarding the PTH, although a study on the Saudi population highlights its involvement in increasing recurrent miscarriage incidence, a lack of significant association was observed with any adverse pregnancy-related outcomes in several studies." (PMID 36420283, 2022).
mood disorder (1 paper, 2022). A cognitive disorder a disturbance in which the person's mood is hypothesized to be the main underlying feature. "One could argue that it would be interesting to deepen the role of PTH by stratifying BD patients according to the severity of illness and patients with mood disorders (both BD and MDD) according to the type of polarity or predominant illness course." (PMID 36144231, 2022). "Three main research directions support the need to implement studies investigating the role of parathyroid hormone (PTH), vitamin D, and serum calcium (Ca++) in mental health conditions, particularly in mood disorders." (PMID 36144231, 2022).
myoma (1 paper, 2024). "In all 5 cases, the diagnosis was established on clinical grounds combined, with low PTH and high PTH-rp levels, the presence of a myoma and imaging ruling out other causes of PTH-rp production." (PMID 39148641, 2024).
myringosclerosis (1 paper, 2008). The formation of dense connective tissue in the TYMPANIC MEMBRANE that does not necessarily cause or lead to loss of hearing. "There was no influence of serum levels of calcium, phosphorus or the PTH on the occurrence of myringosclerosis in the study group." (PMID 18852973, 2008).
neoplastic syndrome (1 paper, 2024). A broad classification for disorders in which the development of neoplasms typically occur in association with a characteristic set of signs or symptoms. "Due to a high level of parathyroid hormone-related peptide (PTHrp), which mimics the action of PTH, malignant tumors can also cause similar symptoms as part of the neoplastic syndrome." (PMID 39213924, 2024).
neuroblastoma (1 paper, 2024). Neuroblastoma (NB) is the most common solid, extracranial childhood tumor. "Furthermore, for the group of to the group of embryonal malignancies it was shown that neuroblastoma cell lines not only respond to PTH in culture but that PTHrP differentially regulates neuroblastoma cell via action on PTH1R." (PMID 39141058, 2024).
neuroendocrine carcinoma (1 paper, 2022). A malignant neuroendocrine neoplasm composed of cells containing secretory granules that stain positive for NSE and chromogranin. "PTH-rP has also been shown to cause HHM in the setting of neuroendocrine carcinoma (NEC)." (PMID 35481321, 2022).
normal-tension glaucoma (1 paper, 2015). "However, recent studies could not show associations of elevated parathyroid hormone (PTH) concentrations and normal-tension glaucoma with altered CIMT." (PMID 26666335, 2015).
ossifying fibroma (1 paper, 2025). A bone benign neoplasm that is located_in the mouth and results_in an overgrowth of gingival tissue due to irritation or trauma. "Jaw tumors with histological diagnosis of ossifying fibroma, accompanied by increased PTH, can indicate initial clinical presentation of HPT-JT." (PMID 40115416, 2025). "Jaw tumors with a diagnosis of ossifying fibroma with concurrent increased PTH should undergo genetic testing for HPT-JT." (PMID 40115416, 2025).
osteocraniostenosis (1 paper, 2024). A lethal skeletal dysplasia characterized by a cloverleaf skull anomaly, facial dysmorphism, limb shortness, splenic hypo/aplasia and radiological anomalies including thin tubular bones with flared metaphyses and deficient calvarial mineralization. "FAM111A gene mutations cause Kenney–Caffey syndrome (KCS) and Osteocraniostenosis (OCS), conditions characterized by short stature, low serum ionized calcium (Ca2+), low parathyroid hormone (PTH), and bony abnormalities." (PMID 38697929, 2024).
Paget’s disease of bone (1 paper, 2025). "Background and clinical significance: Paget’s disease of bone involves anomalies of the bone metabolism; however, the presence of tumor-derivate abnormal parathyroid hormone (PTH) levels does not represent one of these disturbances." (PMID 40981138, 2025).
Pancreatoblastoma (1 paper, 2024). A rare malignant epithelial neoplasm arising from the pancreas. "Our patient represents to our knowledge the first documented case of a PTH-secreting pancreatoblastoma." (PMID 39611185, 2024).
paraplegia (1 paper, 2025). Complete paralysis of the lower half of the body including both legs, often caused by damage to the spinal cord. "More recent research suggests that individuals with complete paraplegia due to SCI exhibit a greater decrease in PTH levels than those with incomplete paraplegia, suggesting a possible association between the severity of neural damage and PTH reduction." (PMID 40176894, 2025).
polio (1 paper, 2025). "However, when comparing post-polio patients with non-polio controls, post-polio patients had significantly lower PTH, non-specific ALP, OC, and CTX levels than non-polio controls." (PMID 40547530, 2025).
Polydipsia (1 paper, 2022). Excessive thirst manifested by excessive fluid intake. "After 8 months without any symptoms, he experienced polydipsia, polyuria, sickness, and vomiting; his serum calcium level was 3.56 mmol/L; and his PTH level was 1,299 pg/ml." (PMID 36303876, 2022).
premenstrual syndrome (1 paper, 2020). "In one of these studies, an association between PTH and E1, but not E2, was noted, while in another, only women presenting with premenstrual syndrome exhibited a mid-cycle elevation of PTH." (PMID 32331456, 2020).
primary brain tumors (1 paper, 2024). "Here, we provide evidence linking higher PTH levels at diagnosis or within the subsequent 5-year period to inferior EFS, but unchanged OS, in childhood embryonal and lymphatic malignancies, as well as in childhood malignant primary brain tumors." (PMID 39141058, 2024).
progeria (1 paper, 2012). "Routine checking of serum calcium, phosphorus and parathyroid hormone will help in the early detection of hypoparathyrodism among children with progeria." (PMID 22251708, 2012). "Routine checking of serum calcium, phosphorus and PTH will help in the early detection of hypoparathyrodism among children with progeria." (PMID 22251708, 2012).
Pseudoarthrosis (1 paper, 2024). A pathologic entity characterized by a developmental defect in a long bone leading to bending and pathologic fracture, with inability to form a normal bony callus with subsequent fibrous nonunion, leading to the pseudarthrosis (or "false joint"). "In this study, 5 of the 15 patients had intact PTH levels within normal range, and 2 of these 5 patients had pseudoarthrosis." (PMID 38398402, 2024).
pterygium (1 paper, 2025). A wedge-shaped fibrovascular lesion arising from the bulbar conjunctiva and extending to the cornea. "Additionally, pterygium patients also had significantly higher levels of parathyroid hormone in comparison to the control group, which is speculative for secondary hyperparathyroidism that is induced as a consequence of long-term hypovitaminosis D." (PMID 40507396, 2025).
pulmonary tuberculosis (1 paper, 2017). A bacterial infection that affects the lungs and is caused by Mycobacterium tuberculosis. "In a prospective observational study of adults with smear-positive pulmonary tuberculosis in Sabah, Malaysia, we measured serial 25D, 1,25D, vitamin D-binding protein (VDBP), albumin, calcium, parathyroid hormone, chest x-ray, week 8 sputum smear/culture and end-of-treatment outcome." (PMID 28449659, 2017).
restless leg syndrome (1 paper, 2023). "Among the non-motor symptoms of PD, the pathogenesis of restless leg syndrome (RLS) is still debated, but it has been associated with the vitamin D/PTH axis in other disease models." (PMID 36873448, 2023).
retinoblastoma (1 paper, 2024). A malignant tumor that originates in the nuclear layer of the retina. "Phosphorylation of rb is PTH-dependent and E2F3, which is a candidate for tumor progression in retinoblastoma belongs to the group of E2F which is targeted and stimulated by PTH." (PMID 39141058, 2024). "Cell lines of retinoblastoma, the entity representing the largest proportion in the group of embryonal malignancies, respond to PTH as well." (PMID 39141058, 2024).
short bowel syndrome (1 paper, 2017). "In the present case, our patient's FGF23 level was quite high (314 pg/mL) and was accompanied by low levels of 1,25(OH)2D, PTH, and tubular maximum reabsorption of phosphate per glomerular filtration rate in addition to malabsorption of phosphate due to short-bowel syndrome." (PMID 28953654, 2017).
sialolithiasis (1 paper, 2024). A concretion in the salivary gland. "Studies on parathyroid hormone and electrolytes in people with sialolithiasis have not revealed any abnormalities." (PMID 39469404, 2024).
skin papilloma (1 paper, 2017). A benign papillary neoplastic growth on the skin composed of epithelial cells and a fibrous stalk. "We demonstrated that high serum PTH in PthMSM-Tg decreased skin papillomas." (PMID 28894263, 2017).
Skull Fractures (1 paper, 2022). Fractures of the skull which may result from penetrating or nonpenetrating head injuries or rarely BONE DISEASES (see also FRACTURES, SPONTANEOUS). "Parathyroid hormone (PTH) is one of the three key hormones that regulate calcium and phosphate homeostasis, so enrichment of the pathway parathyroid hormone synthesis, secretion, and action can promote the recovery of TBSI-induced skull fractures." (PMID 36507346, 2022).
Stillbirth (1 paper, 2022). Death of the fetus in utero after at least 22 weeks of gestation. "The frequency of the PTH variant varied between different complications, 11% IUGR, 5% stillbirth, and 17% VTE which were more prevalent compared to the control." (PMID 36420283, 2022).
tendon disorder (1 paper, 2023). "Broadly speaking, the etiologies of tendon disorder in chronic liver disease are diverse and multifaceted, involving inflammatory cytokines and the immune system, the calcium–vitamin D-parathyroid hormone axis, metabolic homeostasis, drugs, social and environmental interactions, and so forth." (PMID 36981892, 2023).
thrombophilia (1 paper, 2022). A condition characterized by an abnormally high level of thrombi. "Thrombophilia evaluation included the molecular diagnosis of FVL (R506Q), PTH (G20210A) and MTHFR (C677T) variants, measuring the level of AT and PC, and detecting the presence of LA." (PMID 36420283, 2022). "Thrombophilia testing included the molecular diagnosis of FVL (R506Q), PTH (G20210A) and MTHFR (C677T) variants and measuring the level of AT, PC, and detecting the presence of LA." (PMID 36420283, 2022). "Individuals were considered to have thrombophilia when one or more of the following was detected: homozygous or heterozygous of FVL variant (R506Q), homozygous or heterozygous of PTH variant, homozygous MTHFR variant, low level of AT, low level of PC, and detection of LA." (PMID 36420283, 2022). "The thrombophilia molecular diagnosis in this study included FVL, PTH and MTHFR variants." (PMID 36420283, 2022).
tooth agenesis (1 paper, 2024). A tooth disease characterized by failure to develop one or more missing teeth. "Variations in the incidence of tooth agenesis and dental malformation among these groups may be linked to differences in parathyroid hormone metabolism." (PMID 39519162, 2024).
trisomy 21 (1 paper, 2012). A chromosomal disorder consisting of the presence of an extra chromosome 21. "The stimulation of bone mass by intermittent PTH treatment demonstrated the efficacy of the intervention in trisomy 21 and supports the idea that PTH or other potential anabolic treatments, such as anti-sclerostin antibody, may have utility in DS patients with low BMD and low bone turnover." (PMID 22916188, 2012).
TSH resistance (1 paper, 2024). "TSH resistance was described in the totality of the cases (20/20) whereas PTH, GHRH, and LH/FSH resistance were reported in 90%, 69%, and 6% of the cases, respectively." (PMID 39456695, 2024).
ulcerative colitis (1 paper, 2020). An inflammatory bowel disease involving the mucosal surface of the large intestine and rectum. "Biochemical data from three studies included in the present meta-analysis also demonstrated this trend: ulcerative colitis patients had lower concentrations of serum 25-hydroxy vitamin D and higher concentrations of serum parathyroid hormone." (PMID 32072320, 2020).
valvular heart disease (1 paper, 2015). "Also, the lack of data on valvular heart disease and parathyroid hormone levels limited replication of previous studies on this topic." (PMID 25933375, 2015).